KDM6A (lysine demethylase 6A)
Diseases named in the same sentence as KDM6A in open-access papers (continued):
Sharing a sentence is not in itself a finding about the gene and the disease.
cardiovascular disease (2 papers, 2024 to 2026). "Reducing KDM6A levels in human liver cells from females but not males disrupts gene programs involved in lipoprotein regulation linked to cardiovascular disorders." (PMID 41872164, 2026).
hematologic malignancies (2 papers, 2023 to 2025). "Our studies further established an endogenous Kdm6a‐haploinsufficient model that simulates characteristics of KDM6A mutations identified in female patients with hematologic malignancies." (PMID 40365824, 2025). "To date, the involvement of KDM6A haploinsufficiency in hematologic disorders remains largely uncharacterized." (PMID 40365824, 2025). "UTX, also known as KDM6A, functions as a pivotal demethylase, orchestrating an array of processes spanning neurological, oncological, and hematological disorders." (PMID 37951955, 2023).
infectious disease (1 paper, 2022). A disorder directly resulting from the presence and activity of a microbial, viral, or parasitic agent in humans. "With respect to infectious diseases, KDM6A/B inhibition can suppress the growth of infectious pathogens and attenuate the immunopathology precipitated by these pathogens." (PMID 35915507, 2022). "This section reviews the pre-clinical evidence in support of the use of KDM6A/B inhibition in treating various infectious diseases." (PMID 35915507, 2022). "It is mediated by the Jumonji C domain-containing lysine demethylases KDM6A and KDM6B, both of which have been implicated in a wide myriad of diseases, including blood and solid tumours, autoimmune and inflammatory disorders, and infectious diseases." (PMID 35915507, 2022).
neurodegenerative disease (1 paper, 2025). A disorder of the central nervous system characterized by gradual and progressive loss of neural tissue and neurologic function. "Next, we investigated whether Kdm6a affected the RGC survival with two widely used in vivo cell death models, including the ONC and the NMDA receptor‐mediated excitotoxicity, a shared pathological pathway of neurodegenerative diseases." (PMID 39951327, 2025).
neurological disorders (1 paper, 2022). "Ephb6 and Tnik were also downregulated in Kdm6a KO cells derived from reciprocal crosses consistent with immunopathological phenotypes and neurological disorders seen in the syndrome." (PMID 35871105, 2022).
KDM6A also shares sentences with these, for which no sentence is quoted: myelodysplastic syndrome (5 papers); B cell lymphoma (4); breast (4); Hypoglycemia (4); neurodevelopmental disorder (4); Alpha-thalassemia (3); Beckwith-Wiedemann syndrome (3); focal segmental glomerulosclerosis (3); genetic disease (3); microcephaly (3); testicular germ cell tumor (3); autism spectrum disorder (2); CHARGE syndrome (2); chronic myelogenous leukemia (2); clear cell renal cell carcinoma (2); diffuse large B-cell lymphoma (2); Hodgkins lymphoma (2); insulinomas (2); Kabuki syndrome 1 (2); Kleefstra syndrome (2); metabolic syndrome (2); osteoarthritis (2); squamous cell carcinoma (2); 22q11.2 deletion syndrome (1); acinar cell carcinoma (1); Adams-Oliver syndrome (1); Adrenal insufficiency (1); Alagille syndrome (1); allergic contact dermatitis (1); allergic reactions (1).
A further 84 diseases each share a sentence with KDM6A in 1 paper.